EPCAM (epithelial cell adhesion molecule)
Diseases named in the same sentence as EPCAM in open-access papers (continued):
Sharing a sentence is not in itself a finding about the gene and the disease.
pancreatic cancer (continued). "Aiming at strategies to overcome the limitation of using EpCAM as single epitope for enrichment of CTCs, we tested both IsoFlux and KingFisher systems using different EpCAM- and Mucin1 (MUC-1)-coupled magnetic beads to enrich pancreatic tumor cells." (PMID 32290064, 2020). "Unfortunately, due to the low EPCAM expression in pancreatic cancer CTCs, no specific marker is available to identify and isolate this rare cell population." (PMID 33333841, 2020). "These preliminary results suggest that the combination of EpCAM and TSPAN1 could help increase the recovery of isolated pancreatic tumor cells from pancreatic cancer patient’s blood." (PMID 35582043, 2020). "This information did not resolve these early pancreatic cancer cases from more advanced cases defined by these same criteria, in agreement with the demographic analysis of patients with high and low serum EV EpCAM expression." (PMID 31921310, 2019). "Surprisingly, we found cells that displayed both CD163 and EpCAM immunofluorescence in blood from patients with a variety of types of patients, including breast, cervical, ovarian, endometrial and pancreatic cancer, but not in healthy subjects." (PMID 29137267, 2017). "CDF could inhibit sphere formation capacity of pancreatic cancer cell lines and inhibit the expression of the CSC markers CD44 and EpCAM." (PMID 28611316, 2017). "Murine pancreatic cancer Panc02 cells were chosen as an EpCAM-nonexpressed cell lines that do not express extracellular EpCAM under parental cells." (PMID 27886058, 2016). "The bispecific (anti-EpCAM x anti-CD3) trifunctional antibody Catumaxomab was investigated as monotherapy in a phase I/II study, in which this compound was shown to be relatively safe and possibly effective in gastric, colorectal and pancreatic cancer." (PMID 27074785, 2016). "Another study on pancreatic cancer stem-like cells demonstrated that isolated CD44+, CD133+, EpCAM+ cells of human pancreatic cancer behave as cancer stem-like cells, which show more aggressive behavior such as increased cell growth and migration, clonogenicity, and self-renewal capacity." (PMID 24821540, 2014). "CSCs in pancreatic cancer cases are characterized by expression of the cell surface markers CD44, CD24, and epithelial-specific antigen (ESA; epithelial cell adhesion molecule [EpCAM])." (PMID 24325450, 2013). "Epithelial cell adhesion molecule (EPCAM) is highly expressed in numerous solid tumors, and it has recently been shown to be expressed on tumor-initiating cells from breast, prostate, colon, and pancreatic cancer." (PMID 24073010, 2013). "Taken together, this study demonstrates the central role of Notch signalling pathway in pancreatic cancer pathogenesis independent of their tumorigenicity and that pancreatic tumor initiating CD44+/EpCAM+ cells are down regulated by GSI." (PMID 23094026, 2012). "Second, the EpCAM CAR-T cells could elicit antigen-dependent proliferation, cytokine secretion and cytotoxicity to target tumor cells in vitro in both two-dimensional and three-dimensional pancreatic tumor models." (PMID 41417221, 2025). "Interestingly, the PANC-1 CSC pancreatic cancer spheroids could be subcultured several times for at least seven generations, and these CSC pancreatic cancer spheres, again, contained only 2.8–7.5% of CD44+CD24+EpCAM+ cells after prolonged culture." (PMID 34885233, 2021). "A previous work has shown that high numbers of MUC-1pos/EpCAMpos CTCs correlate with shorter overall survival in patients with pancreatic cancer, and data suggest that MUC-1 and EpCAM might identify different subtypes of CTCs in pancreatic, but also in ovarian and metastatic breast cancer." (PMID 32290064, 2020).
pancreatic cancer (continued). "Validation of the method using clinical samples from pancreatic cancer patients with EGFR (epidermal growth factor receptor), EpCAM (epithelial cell adhesion molecule), HER2, and MUC1 (mucin-1) antibodies, indicated that the method could be used for profiling scarce cells from clinical samples." (PMID 31762967, 2019). "CSC target genes (CD24, EpCAM, BMI1, and LGR5) were also downregulated after JNKi treatment, suggesting that the JNK pathway might play a role in the regulation of CSCs in pancreatic cancer." (PMID 26840266, 2016). "After an initial enumeration of EMTCTCs in patients with pancreatic cancer for use in clinical prognostication, further interrogation was not possible as the cell stains had occupied all fluorescent channels (i.e. FITC conjugated CK, PE conjugated EpCAM, DAPI and Cyanine5 conjugated CD45)." (PMID 27647345, 2016). "For example, the proposed link between low EPCAM expression and the absence of lymph node metastasis in HCC, and the suggestion that CXCR2-mediated ligand competition underlies the hypovascularity of pancreatic cancer, are intriguing, but not directly demonstrated by the present data." (PMID 41228323, 2025). "Therefore, the overexpression of GAS2L1 in pancreatic CTCs and its utility in combination with EPCAM as a cell surface marker represent a promising approach for detecting and isolating pancreatic CTCs, and highlights the potential of GAS2L1 as a novel biomarker for pancreatic cancer." (PMID 37720505, 2023). "However, recent development of a cancer immunotherapy using an anti-EPCAM monoclonal antibody conjugated with α-AMA demonstrated clear growth suppression effects in a human pancreatic cancer mouse skin xenograft model without systemic side effects even at a dose of 0.1 mg/kg40." (PMID 27181033, 2016). "Therefore, ALB was nontoxic to pancreatic cancer cells on functional targeting of EpCAM or muc1." (PMID 27886058, 2016). "The combination of EPCAM/GAS2L1 surface protein stainings may increase the detection rate and comprehensiveness of CTC studies in pancreatic cancer without limiting the availability of the isolated CTCs for downstream analyses." (PMID 33333841, 2020).
liver cancer (131 papers, 2011 to 2025). An epithelial or non-epithelial malignant neoplasm that arises from the liver. "As EpCAM is a marker of liver cancer stem cells, we further evaluated the expression of genes encoding EpCAM and DKK-1 using EpCAM+/− cells sorted from Huh7 cells." (PMID 35269944, 2022). "EpCAM is a well-characterized surface marker of liver cancer cells, and the presence of EpCAM-positive CTCs has been previously associated with vascular invasion, increased serum AFP, more advanced HCC stage, and increased recurrence rates after surgery." (PMID 34069569, 2021). "C66Y EpCAM is an exemplary TY-1 domain EpCAM cancer-associated mutation identified in a liver cancer specimen." (PMID 33980181, 2021). "To determine how EpCAM mutations affect cancer biology we studied C66Y, a damaging TY-1 domain mutation identified in liver cancer, as well as 13 other cancer-associated EpCAM mutations." (PMID 33980181, 2021). "Univariate analysis with log-rank test showed that EpCAM positivity was significantly associated with poor prognosis of liver cancer patients (P = 0.028)." (PMID 29497050, 2018). "Moreover, EpCAM is highly expressed in H-ChC samples and associated with poor prognosis of patients with liver cancer." (PMID 29497050, 2018). "We detected the expression of CYPJ, CD86 (a marker for M1 TAMs), CD163 (a marker for M2 TAMs), CD8 (a marker for CD8+ T cell), and EpCAM (a marker for tumor cells) in tissues from liver cancer patients using the mIHC method." (PMID 40520002, 2025). "In the past decades, some cell markers have been used in cancer treatment; for example, CD133 and EpCAM have been widely studied as stem cell markers in liver cancer." (PMID 40006612, 2025). "In this study, the levels of p-AKT, β-catenin, c-Myc, and EpCAM in hepatic cancer cells were decreased with the knockdown of SLC1A4, and the K63-dependent ubiquitin level of AKT protein was decreased with the knockdown of SLC1A4." (PMID 39949345, 2025). "DAPT reduced EpCAM+ and EpCAM− Huh7 cell fractions and inhibited liver cancer growth, prolonging survival in an in vivo model." (PMID 40890130, 2025). "In highly malignant human liver cancer tissue, EpCAM- and CD90-positive cancer cells exist adjacent to each other." (PMID 40253402, 2025). "Subsequent research revealed that liver cancer spheroids rich in patient-derived CSC as well as cancer stem cells (CSCs) selected for epithelial cell adhesion molecule (EpCAM) or differentiation cluster 133 (CD133) showed a substantial increase in SHP2." (PMID 38504984, 2024). "EpCAM (epithelial cell adhesion molecule) is a protein that is expressed on the surface of many cancer cells, including liver cancer cells." (PMID 39417449, 2024). "The results showed that the expression levels of CK19 (p < 0.05) and EpCAM (p < 0.05) in liver cancer tissues of C. sinensis-infected HCC patients were significantly higher than those in noninfected C. sinensis patients." (PMID 38285640, 2024). "BMP9 has the ability to induce cancer stem cell properties in a specific subtype of liver cancer stem cells (LCSCs) that are characterized by the presence of an epithelial cell adhesion molecule (EpCAM)." (PMID 39199400, 2024). "Given the differential expression of EpCAM in CTCs, this provides us with valuable insights into the heterogeneity of liver cancer." (PMID 39280341, 2024). "The rAd carrying PTEN (Ad5-PTEN) is an effective anti-liver cancer drug; aptamer EpDT3 can specifically bind to epithelial cell adhesion molecule (EpCAM) and target EpCAM-positive cells." (PMID 38167076, 2024). "We utilize a PSINR to specific capture and release the EpCAM + CTCs and EpCAM- CTCs of liver cancer at the same time." (PMID 39280341, 2024). "IFN-γ was highly expressed in liver NK cells, which can promote the progression of liver cancer through the EpCAM–EMT axis." (PMID 38187284, 2024).
liver cancer (continued). "Consistent with the primarily embryonal histological features, GSEA results showed that ABC-Myc tumors had significant upregulation of cancer stem cell signatures including “liver cancer with upregulated EpCAM” and “undifferentiated cancer”." (PMID 37414763, 2023). "In human liver cancer samples, EpCAM is often co-expressed with EMT marker proteins and cancer stem cell biomarkers." (PMID 36990999, 2023). "To address the heterogeneity of HCC cells in terms of CSCs, we first applied Gaussian mixture model (GMM) clustering to examine the potential clusters in 17 liver cancer cell lines based on EpCAM and CD90 expression, as detected on the RPPA analysis." (PMID 34445353, 2021). "To further investigate the effect of miR-22-3p on the stemness of liver cancer stem cells, we detected the positive populations of EPCAM and CD133 in HCC cells." (PMID 34019487, 2021). "In this study, we classified 17 liver cancer cell lines based on the expression of EpCAM and CD90 CSC markers." (PMID 34445353, 2021). "Collectively, our findings suggest that JMJD2D promotes LCSC self-renewal by enhancing EpCAM and Sox9 expression via Wnt/β-catenin and Notch signaling pathways and is a potential therapeutic target for liver cancer." (PMID 33434575, 2021). "EpCAM is a known Wnt/β-catenin signaling target gene and an important liver cancer stem cell marker." (PMID 34458250, 2021). "Positivity for epithelial cell adhesion molecule (EpCAM) and cytokeratin-19 (CK-19) which are markers of liver cancer stem cells expressed in hepatic progenitor cells have been identified as poor prognostic factors for recurrence." (PMID 34638613, 2021). "A number of surface markers for liver cancer stem cell (LCSC) subpopulations (EpCAM, CD133, CD44, CD13, CD90, OV-6, CD47, and side populations) in HCC have been identified." (PMID 32466488, 2020). "In liver cells, RNA interference-based blockage of EpCAM significantly inhibited the self-renewal and differentiation capacity of hepatic cancer stem-like cells in vitro and in vivo." (PMID 32987767, 2020). "EpCAM+-rich cell subpopulations isolated from HCC present liver cancer stem cell features, which promote self-renewal, differentiation, and invasiveness." (PMID 32466488, 2020). "EpCAM, one of the first markers identified to isolate putative liver cancer stem cells (LCSCs), is normally expressed by hepatoblasts/human hepatic progenitor cells in the liver, but it is not expressed by mature hepatocytes." (PMID 32408542, 2020). "Liver cancer cells with stem cell phenotypes generally highly express well-known stem cell-related molecular markers, such as Oct-4, Sox-2, Nanog, Epithelial cell adhesion molecule (EpCAM), CD90, CD133, and CD44." (PMID 31185668, 2019). "CBX8 showed significantly elevated expression in sorted primary EpCAM+ or CD133+ liver cancer cells relative to matched EpCAM− or CD133− cells." (PMID 30718464, 2019). "Epithelial cell adhesion molecule (EpCAM) is a known surface marker of liver cancer stem cells (LCSCs) and a prognostic marker of HCC." (PMID 30593276, 2018). "By targeting the markers cluster of differentiation (CD) 90, CD44, CD133 and epithelial cell adhesion molecule (EpCAM), it has proven possible to differentiate between liver cancer stem cells (LCSC) and liver cancer cells." (PMID 30326865, 2018). "We used CD133/CD44/CD24/EpCAM MicroBeads to isolate hLCSCs from human liver cancer cell line Huh7 by detecting the markers of hLCSCs, including CD133, CD44, CD24 and EpCAM." (PMID 29602239, 2018). "We then analyzed protein levels of select stem cell markers inclusive of EpCAM and C-kit by immunohistochemistry using samples from 75 liver cancer patients." (PMID 29497050, 2018). "To further validate the stem features of H-ChC, we performed immunohistochemical staining with stem cell markers including c-kit and EpCAM in FFPE tissue specimens obtained from 75 liver cancer patients." (PMID 29497050, 2018).
liver cancer (continued). "Overexpression of FGF19/FGFR4 significantly correlated with EpCAM as a marker of hepatic cancer stem cells within the fatty-steatosis-cirrhosis-HCC sequence." (PMID 27447573, 2016). "Overexpression of FGF19/FGFR4 significantly correlated with EpCAM as a marker of hepatic cancer stem cells within the fatty liver-steatosis-cirrhosis-HCC sequence." (PMID 27447573, 2016). "It is known that EpCAM, a cell surface antigen and mediator of cellular adhesion and signaling, is a specific biologic marker for hepatic cancer stem cells." (PMID 27447573, 2016). "EpCAM and Wnt–β-catenin signaling are connected, and both play a role in the maintenance of hepatic cancer stem cells." (PMID 26984381, 2016). "This toxin was used to create a novel immunotoxin targeting EpCAM and was demonstrated to be effective in the treatment of liver cancer." (PMID 27669301, 2016). "Hepatic cancer stem cells have been identified by several markers, including EpCAM, CD90, CD133, CD44, CD24, and CD13." (PMID 26556861, 2015). "To compare the growth and gene expression between liver cancer stem cell and unstemic liver cancer cells, we isolated the liver cancer stem cells from human liver cancer cell line Huh7 by CD133/CD44/CD24/EpCAM MicroBead according to the schematic digram." (PMID 26513297, 2015). "Several different markers can be identified such as CD133, CD90, CD44, CD326 (EpCAM) or by selecting the side population (SP) cells by Hoechest dye-staining in order to isolate CSCs from liver cancers." (PMID 26097877, 2015). "EpCAM(+) HCC cells displayed hepatic cancer stem cell-like traits, including the abilities to self-renew and differentiate." (PMID 26540343, 2015). "CD44, CD90, CD133, and EpCAM are the cell–surface markers of liver cancer stem cells, further, Oct-4 and BMI-1 are the key ‘stemness’ genes in CSCs from various cancers." (PMID 24806207, 2014). "In this study, a comprehensive analysis of differential expression of miRNAs and their important targets were performed between EpCAM+ fetal liver cells and EpCAM+ liver cancer cells induced by DEN." (PMID 23936298, 2013). "Our previous report also revealed that the relative expression levels of miR-92b, miR-21, miR-34c, miR-10b, and let-7i in EpCAM+ liver cancer cells compared to fetal liver cells were increased (P<0.05)." (PMID 23936298, 2013). "The EpCAM+ cells were sorted out from unfractionated fetal liver cells and liver cancer cells using the FACS analysis and miRNA expression profiles of two groups were screened through microarray platform." (PMID 23936298, 2013). "Clinical research has reported that patients with high Rictor or EpCAM mRNA expression in isolated liver cancer had a higher rate of relapse." (PMID 24312415, 2013). "The EpCAM+ cells were sorted out from unfractionated fetal liver cells and liver cancer cells using FACS analysis; 2.5%±1.8% of the fetal liver cells and 5.7%±1.2% of the liver cancer cells were expressing the EpCAM receptors." (PMID 23936298, 2013). "The miRNAs microarray analysis showed deregulation of 78 miRNAs in EpCAM+ liver cancer cells as compared with EpCAM+ fetal liver cells (P<0.05)." (PMID 23936298, 2013). "In 2009, EpCAM+ HCC cells were identified as possible liver cancer stem cells, and the expression of EpCAM is regulated by Wnt/β-catenin signaling." (PMID 23170877, 2012). "In MHN, the most up-regulated genes (with a fold-change >10) included several genes that also identify hepatic cancer stem cells, most notably EpCAM, CK19 and CK7." (PMID 23185381, 2012). "In this regard, the expression of EpCAM, a putative liver cancer stem cell (CSC) marker and a β-catenin/TCF-4 downstream target gene product, was not upregulated in these cells." (PMID 22768190, 2012). "The level of epithelial cell adhesion molecule (EpCAM), which has also been shown to be highly expressed in liver cancer stem cells, was 2.6-fold higher in the CD133+ subpopulations compared with the CD133- subpopulations." (PMID 23170877, 2012).